RN7SL216P (RNA, 7SL, cytoplasmic 216, pseudogene)
Gene: Miscellaneous RNA gene on chromosome 3 (25,020,166 to 25,020,463, reverse strand). Ensembl gene ENSG00000244404.
Homologues: Orthologues: chimpanzee Metazoa_SRP (100% identical), macaque Metazoa_SRP (95% identical). Paralogues in human: RN7SL2 (80% identical), RN7SL1 (80% identical), RN7SL3 (79% identical), RN7SL45P (78% identical), RN7SL709P (78% identical), RN7SL122P (78% identical), RN7SL660P (78% identical), RN7SL597P (77% identical), RN7SL127P (77% identical), RN7SL186P (77% identical), RN7SL386P (77% identical), RN7SL621P (77% identical), and 703 more.